CASR (calcium sensing receptor)
Diseases named in the same sentence as CASR in open-access papers (continued):
Sharing a sentence is not in itself a finding about the gene and the disease.
neuroblastoma (16 papers, 2013 to 2022). Neuroblastoma (NB) is the most common solid, extracranial childhood tumor. "In contrast, reduced expression of CaSR has been observed in colorectal, pancreatic and neuroblastomas cancers, which was associated with an increase in the progression of malignancy." (PMID 36348350, 2022). "In particular, promoter 2 hypermethylation and histone modifications of the CaSR gene were found in aggressive neuroblastomas associated with Myc related gene (MYCN)-amplification and undifferentiated histology." (PMID 31336912, 2019). "The work also showed that the malignant nature of neuroblastoma is associated with the inactivation of CaSR gene in patients." (PMID 26010602, 2015). "To gain further insight into the genetic mechanisms responsible for its inactivation in malignant neuroblastomas, we have now analyzed the three clustered genetic variants at coding exon 7 that have been described to influence CaSR activity." (PMID 23533647, 2013). "Finally, while several evidences showed that epigenetic modifications are involved in silencing the CaSR in neuroblastoma, the mechanisms responsible for receptor loss in parathyroid tumors have not yet been elucidated." (PMID 31336912, 2019). "A particular region of the CpG island encompassing CASR gene promoter 2 was found to be hypermethylated in 25% primary neuroblastomas, in association with reduced CaSR mRNA expression, MYCN amplification, undifferentiated histopathology and other factors of poor outcome." (PMID 27242543, 2016). "Studies on human patient samples with relatively superior prognostic variables like low clinical stage and clinical risk and age of diagnosis below one year had confirmed CaSR expression on nearly 50% of both fully and partially differentiating neuroblastoma, along with the expression of PTHrP." (PMID 26010602, 2015). "Thus, its association with metastatic disease and poor outcome would add to our previous data and further support that inactivation of the CaSR gene is a mechanism associated with neuroblastoma malignant behavior." (PMID 23533647, 2013). "Moreover, we provide new evidence supporting that inactivation of the CaSR gene is a mechanism associated with neuroblastoma malignant behavior." (PMID 23533647, 2013). "Expression level and activity of the CaSR were linked to risk, incidence, recurrence, or lethality of various cancers, such as prostate, breast, colorectal, ovarian cancer, or neuroblastoma, cancers where vitamin D insufficiency might also be involved in etiology." (PMID 27803671, 2016). "In addition, when non-synonimous genetic variants located at the intracellular tail encoded by exon 7 of the CASR gene were analyzed in a cohort of neuroblastoma patients, a haplotype including a polymorphism considered to mildly reduce CaSR activity was associated with poor outcome." (PMID 27242543, 2016). "Genetic variants at the carboxy terminal of the CaSR were studied and three single nucleotide polymorphisms at rs1042636, rs1801725 and rs1801726 were observed and this tri-locus haplotype could be considered as an outcome predictor in neuroblastoma patients." (PMID 26010602, 2015). "In the context of neuroblastic tumors, the association of this potentially less active CaSR with metastatic disease and poor outcome would add to our previous results indicating that this gene is silenced by genetic and epigenetic mechanisms in aggressive neuroblastomas." (PMID 23533647, 2013). "The activation of CaSR with cinacalcet, a positive allosteric modulator of CaSR, reduces neuroblastoma tumor growth by promoting differentiation, endoplasmic reticulum (ER) stress and apoptosis." (PMID 35457141, 2022). "Our results of an eCa2+-dependent elevation in [Ca2+]i confirm a role for CaSR in the modulation of [Ca2+]i in N18TG2 neuroblastoma cells, as previously demonstrated." (PMID 36230909, 2022).
neuroblastoma (continued). "Ectopic CaSR expression (or acute exposure to calcium) in neuroblastoma cells facilitates apoptosis, which relies on a sustained activation of ERK1/218." (PMID 29348629, 2018). "In neuroblastoma, CaSR mRNA expression significantly correlated with several factors associated with good outcome such as age at diagnosis <1 year, low clinical stage and differentiated histology." (PMID 27242543, 2016). "CaSR also plays significant roles during differentiation of neuroblastoma, a developmental tumor of the peripheral nervous system (PNS)." (PMID 27242543, 2016). "Accordingly, ectopic overexpression of the CaSR significantly reduced the proliferative and tumorigenic capacities of neuroblastoma cells." (PMID 26893368, 2016). "Among available neuroblastoma cell lines, only LA-N-1 cells exhibited detectable endogenous CaSR mRNA expression." (PMID 26893368, 2016). "More importantly, cleavage of caspase-3 and decreased cell viability induced by cinacalcet in CaSR-positive neuroblastoma cells were significantly reduced by U73122." (PMID 26893368, 2016). "In all, these data provided functional evidence of the biological relevance of CaSR epigenetic silencing in neuroblastoma biology." (PMID 27242543, 2016). "We have previously reported that acute exposure to high extracellular calcium (Ca2+o) concentrations following serum deprivation induces apoptotic cell death in CaSR-overexpressing neuroblastoma cells." (PMID 26893368, 2016). "On the other hand, several lines of evidence support a role for CaSR in promotion of cell differentiation and inhibition of proliferation in neuroblastoma, a tumor arising from precursor cells of developing PNS." (PMID 27242543, 2016). "In unfavorable neuroblastomas CaSR is silenced by epigenetic and genetic mechanisms, while in parathyroid tumors CaSR loss is independent of DNA methylation." (PMID 27803671, 2016). "In summary, studies conducted in neuroblastoma indicate that CaSR promotes differentiation and inhibits proliferation in this malignancy." (PMID 27242543, 2016). "More importantly, neuroblastoma models show that pharmacological modulation of CaSR activity can provide novel therapeutic opportunities." (PMID 27242543, 2016). "Most unfavorable neuroblastomas exhibit low levels of CaSR expression, and enforced expression of the receptor notably reduces neuroblastoma cell proliferation and tumorigenicity." (PMID 26893368, 2016). "CaSR protein expression was also present in the neuroblastoma metastasis from which a PDX model was generated." (PMID 26893368, 2016). "In undifferentiated unfavourable neuroblastoma, CaSR expression is silenced by several genetic and epigenetic mechanisms." (PMID 26010602, 2015). "[Ca2+]i regulated apoptosis in neuroblastoma involves the intrinsic pathway and the activation of CaSR." (PMID 26010602, 2015). "Overall and event-free survival of patients diagnosed with neuroblastomas according to CaSR haplotypes." (PMID 23533647, 2013). "We have previously reported that the CaSR gene is expressed in differentiated, benign neuroblastic tumors but silenced by genetic and epigenetic events in undifferentiated, unfavorable neuroblastomas." (PMID 23533647, 2013). "Recently, we have also shown that the CaSR gene is silenced by genetic and epigenetic mechanisms in unfavorable neuroblastomas." (PMID 23533647, 2013). "An anti-tumoral effect of CasR has also been observed in neuroblastoma." (PMID 33113952, 2020). "In contrast, several lines of evidence have suggested that the CaSR plays an opposite role in developing nervous system tumors, as the activation of the receptor leads to growth inhibition and induction of differentiation in many neuroblastoma cell lines." (PMID 31336912, 2019).
neuroblastoma (continued). "Altogether, our published data were consistent with the hypothesis that the CaSR exerts tumor-suppressor functions in neuroblastoma." (PMID 26893368, 2016). "Moreover, upon neuroblastoma differentiation induction, increased CaSR expression was seen both in clinical specimens obtained after treatment, and in vitro, at early phases of neuronal differentiation induced by retinoic acid." (PMID 27242543, 2016). "Thus, increase of CaSR expression upon cinacalcet treatment would reduce neuroblastoma aggressiveness by itself, and additionally promote a more pronounced response to the drug over time." (PMID 26893368, 2016). "In addition, Masdival and co-workers reported CaSR expression in developmental malignancy, confirming that both CaSR and PTHrP are expressed in differentiated favourable neuroblastoma and are unregulated upon inducing differentiation." (PMID 26010602, 2015). "Thus, it was clear that CaSR was over expressed in neuroblastoma cells and when exposed to Ca2+ cells underwent apoptosis via ERK1/2signalling cascade." (PMID 26010602, 2015). "Moreover, upon ectopic overexpression and reactivation of the CaSR, neuroblastoma cells undergo apoptosis." (PMID 23533647, 2013). "Depending on the tissue where the CaSR is expressed, the CaSR can either promote cancer development, thus behaving as an oncogene, such as in gastric, breast, prostate, and renal cancer, or as a tumor suppressor, such as in colorectal, endometrial, parathyroid cancer, and neuroblastoma." (PMID 36467702, 2022). "Furthermore, neuroblastoma cell lines stably transfected with the full-length CaSR exhibited a reduced proliferation capacity and resulted in ERK1/2-mediated apoptosis upon activation of the CaSR with high extracellular Ca2+, which is in line with the receptor-mediated effect in hypoxic processes." (PMID 31336912, 2019). "Thus, we next sought to evaluate whether cinacalcet, an allosteric activator of the CaSR approved for clinical use, might reduce neuroblastoma tumor cell growth." (PMID 26893368, 2016). "However, based on our previous results, we hypothesized that their ability to modify CaSR function might influence neuroblastoma phenotype and thus clinical outcome." (PMID 23533647, 2013). "We observed functional interactions between the CB1R and CaSR activation in regulating [Ca2+]i, and these interactions are dependent on eCa2+ with the participation of nonCB1/CB2 receptors in neuroblastoma cells." (PMID 36230909, 2022). "Since the CaSR monitors the extracellular Ca2+ environment, our studies were performed in the N18TG2 neuroblastoma cell model that endogenously expresses both CB1R and CaSR." (PMID 36230909, 2022). "Our first analyses were based on our previous findings and showed that acute exposure to cinacalcet triggers ER stress and apoptosis in CaSR-positive, MYCN-amplified neuroblastoma cells, dependent on phospholipase C activation." (PMID 26893368, 2016). "Next, we reported that the CaSR gene is silenced by genetic and epigenetic mechanisms in MYCN-amplified, unfavorable neuroblastomas." (PMID 26893368, 2016). "Acute CaSR activation did not induce PTHLH upregulation in neuroblastoma cell lines exhibiting endogenous CaSR expression." (PMID 31293052, 2019). "Given that CaSR has been shown to stimulate PTHLH production in other cellular contexts, we initially assessed whether this was also the case in neuroblastoma." (PMID 31293052, 2019). "As expected based on our previous reports, PTHLH was not under the control of the CaSR in neuroblastoma." (PMID 31293052, 2019). "When the same neuroblastoma cell lines were allowed to proliferate in the presence of concentrations lower than IC50 for 5 days, a moderate dose- and time-dependent decrease of cell viability was detected in CaSR-positive cells." (PMID 26893368, 2016).
neuroblastoma (continued). "Interestingly, authors observed that the CaSR, which results in low or non-expression in undifferentiated neuroblastomas, became up-regulated upon inducing differentiation with retinoic acid." (PMID 31336912, 2019).
myocardial infarction (15 papers, 2016 to 2025). Gross necrosis of the myocardium, as a result of interruption of the blood supply to the area, as in coronary thrombosis. "Moreover, CaSR polymorphisms are known to be associated with coronary artery diseases (CADs) such as myocardial infarction (MI) and atherosclerosis." (PMID 33804544, 2021). "Our previous study revealed that increased expression of myocardial CaSR in atherosclerotic rats could enhance the risk of myocardial infarction." (PMID 33149870, 2020). "When the vascular smooth muscle CaSR is underexpressed, such as in hypercalcemia, protection against myocardial infarction should be reduced." (PMID 36580074, 2022). "In order to observe the changes of CaSR after myocardial infarction at different time points, the expression of CaSR was detected by western blotting at weeks 1, 2 and 4 after establishment of AMI models." (PMID 33149870, 2020). "In vivo experiments showed that CASR could significantly improve myocardial infarction, blood stasis, and blood lipid levels and regulate the PI3K/AKT/mTOR signaling pathway in CHD rats." (PMID 36016561, 2022). "It was found that CaSR expression was gradually increased over time after myocardial infarction, and mESCs transplantation treatment could reduce the CaSR expression except in 2nd week." (PMID 33149870, 2020). "The effects here described are in accordance with recent findings indicating that CaSR activation participates in many inflammatory processes, such as recognition of necrotic cells and pathologies like asthma, myocardial infarction, and sepsis." (PMID 27660614, 2016). "Collectively, with increased duration of rat myocardial infarction, the CaSR expression was gradually increased, and apoptosis and oxidative stress were increased, and these effects could be significantly enhanced by the CaSR agonist." (PMID 33149870, 2020). "However, the role of CaSR at different stages after myocardial infarction or ESC transplantation treatment remains unknown." (PMID 33149870, 2020). "Moreover, tail vein injection of Calhex231 or Calindol could enhance or weaken the effects of mESCs transplantation therapy; it was indicated that the increased CaSR expression was involved in the occurrence of myocardial infarction." (PMID 33149870, 2020). "In acute myocardial infarction (AMI) rats, CaSR expression was increased over time, and the inhibition of the CaSR by Calhex231 enhanced the efficacy of mESC transplantation for the treatment of AMI by inhibiting apoptosis and oxidative stress." (PMID 36231037, 2022). "Therefore, to further understand the therapeutic mechanism of CASR in the treatment of CHD, we tested a hypothesis that CASR regulates lipid metabolism and improves myocardial infarction through its constituents in the plasma, to treat CHD." (PMID 36016561, 2022).
parathyroid tumors (14 papers, 2016 to 2025). "In the Basic Research cluster, its hotspots focus on Multiple endocrine neoplasia type 1, Parafibromin Immunostainings of Parathyroid Tumors, MEN1 Mutations and Calcium-Sensing Receptor and Vitamin D Receptor." (PMID 35198447, 2022). "The YAP1 variable downregulation observed in parathyroid tumor tissues resembles the extensively described heterogeneous expression of CASR in these tumors." (PMID 33670622, 2021). "The YAP1 expression pattern detected in parathyroid tumors reflects the heterogeneous expression of the CASR protein, which has been extensively reported in previous studies." (PMID 33670622, 2021). "It is overexpressed in parathyroid tumours and attenuates CaSR-mediated signalling." (PMID 35805976, 2022). "In line with our hypothesis, parathyroid tumor cells with an intense CASR staining showed YAP1 nuclear expression." (PMID 33670622, 2021). "Aberrant expression of CASR is frequently found in parathyroid tumors." (PMID 34054720, 2021). "VDR was found to be decreased in parathyroid tumors, which may promote parathyroid cell proliferation, set-point for calcium sensing receptor (CaSR), and influence the clinical manifestation of HPT." (PMID 33910638, 2021). "Indeed, we detected a great variability in the number of cells with YAP1 positive nuclear immunostaining, and these findings are likely related to the variable downregulation of the CASR in parathyroid tumors." (PMID 33670622, 2021). "The fact that one group displays calcium responsiveness similar to the reported value for wild‐type CASR implies that a subset of parathyroid tumours may be intrinsically capable of appropriate calcium sensing to some degree." (PMID 26638194, 2016). "Therefore, receptor and post-receptor downregulation of the CASR signaling may be associated with downregulated WNT5A, in line with the previously reported WNT5A downregulation in parathyroid tumors." (PMID 33670622, 2021). "However, by comparison to prior cell culture-based CASR signaling studies using buffers similar to those used in our study, the calcium sensitivity of the parathyroid tumor tissue tested here is clearly well below published measures of wild type CASR reactivity determined in vitro." (PMID 27537691, 2016). "Contextual cues from the physical microenvironment of the intact parathyroid are likely to play a vital role in the subcellular localization and trafficking of CASR, and the disruption of tissue organization by parathyroid tumors may thus compromise native calcium responsiveness." (PMID 27537691, 2016). "In molecular genetic studies of sporadic parathyroid tumors reported to date, somatic inactivation of the CASR gene has not been described." (PMID 33716975, 2021). "This demonstration of biochemical heterogeneity implies multifactorial molecular mechanisms of calcium-sensing failure rather than uniform suppression of CASR activity as the operative defect in PHPT culprit parathyroid tumors." (PMID 27537691, 2016).